CTLA4 (cytotoxic T-lymphocyte associated protein 4)
Diseases named in the same sentence as CTLA4 in open-access papers (continued):
Sharing a sentence is not in itself a finding about the gene and the disease.
tumor (continued). "It was suggested that MSI represents a classical example of adaptive resistance in which an active immune Th1/CTL microenvironment results in a compensatory induction of checkpoints, including PD-1, PD-L1, CTLA-4, IDO, and LAG-3, which protect the tumor from apoptosis." (PMID 26605342, 2015). "Here, we used network analysis of gene expression data from responding versus non-responding tumours from anti-CTLA4 treated mice to identify repurposed drugs that further improve the efficacy of CTLA4 blockade." (PMID 26193793, 2015). "For patients of Group 2 (CTLA-4high tumor cells, densityhigh CTLA-4+ lymphocytes), high levels of soluble CTLA-4 in the tumor microenvironment would suppress TIL anti-tumor immunity to no stronger than that of the densitylow groups, which would lead to poor prognosis." (PMID 25893809, 2015). "Moreover, 64Cu-DOTA-anti-CTLA-4 mAb showed higher tumor-to-blood and tumor-to-muscle ratios than 64Cu-DOTA-Control IgG (tumor-to-blood ratio: 0.58±0.03 vs. 0.40±0.02, p<0.001; tumor-to-muscle ratio: 8.48±0.63 and 5.31±0.35, p<0.01)." (PMID 25365349, 2014). "Tumor growth and survival time were not markedly different between the anti-CTLA-4 antibody alone group and the control group." (PMID 24686897, 2014). "Unlike CTLA-4 negative regulation PD-1/PDL-1 takes place in the peripheral tissue/tumor during the effector phase of T-cell activation." (PMID 25374843, 2014). "Interestingly, Allard found that anti-CD73 mAb significantly enhanced the activity of both anti-CTLA-4 and anti-PD-1 mAbs against MC38-OVA (colon) tumor, RM-1 (prostate) subcutaneous tumors, and metastatic 4T1.2 breast cancer in mice models." (PMID 25126561, 2014). "In our preliminary biodistribution analyses, tumor uptake on 64Cu-DOTA-anti-CTLA-4 mAb was not significantly higher than that on 64Cu-DOTA-Control IgG at 24 h after administration of the probes (data was not shown)." (PMID 25365349, 2014). "However in cancers, tumor infiltrating T-cells are often inhibited by both PD1 and CTLA-4 stimulation." (PMID 25101247, 2014). "Here we show that the improved response of 4T1 tumor-bearing mice seen in the absence of iNKT cells is not unique to anti-CTLA-4-based immunotherapy." (PMID 25349699, 2014). "However, CTLA-4 expression was extremely low in the cultured CT26 cells and the CT26 tumor tissues of tumor-bearing BALB/c nude mice." (PMID 25365349, 2014). "In initial studies, significant anti-tumor responses were observed in mice bearing immunogenic tumors; however, poorly immunogenic tumors did not respond to anti-CTLA-4 antibody monotherapy." (PMID 24686897, 2014). "When compared to non-tumor bearing mice, our results show that there is indeed an influx of CD4+ and CD8+ T cells into the brains from the groups in which immunotherapy with 4-1BB activation and CTLA-4 blockade is employed." (PMID 25013914, 2014). "Notably, the combination of anti-CTLA-4 and GVAX vaccination significantly increased the number of tumor infiltrating CD4 T cells in the prostate gland, as compared to GVAX therapy alone." (PMID 23557194, 2013). "In order to determine the optimal treatment schedule in terms of timing of both anti-CTLA-4 and gemcitabine, we treated AB1-HA tumor-bearing mice with three different regimes: gemcitabine followed by anti-CTLA-4, concomitant combination therapy, and anti-CTLA-4 followed by gemcitabine." (PMID 23626745, 2013). "As expected, anti-CTLA-4 treatment alone did not significantly increase the percentage of divided HA-specific CD8 T cells in either tumor bearing or non-tumor bearing mice." (PMID 23557194, 2013). "To more directly examine the immunological effects of combination treatment in tumor-bearing mice, we performed a series of studies varying the relative timing of vaccination and CTLA-4 blockade, in either non-transgenic or tumor-bearing ProHA × TRAMP mice." (PMID 23557194, 2013).
tumor (continued). "By blocking the interaction between CTLA-4 expressed by T cells and B7 ligands expressed by APC, these mAbs may promote further activation and expansion of tumor-specific T cells." (PMID 23634660, 2013). "Most CTLA-4 expressing T cells are not tumor-specific and ctla-4 KO mice exhibited a lethal autoimmune and hyperimmune phenotype, predicting immune toxicity in human CTLA-4 blockade." (PMID 24348481, 2013). "First, the results here suggest that the transfer of autologous T-cells and immune stimulation with CTLA-4 inhibition are not equivalent strategies to trigger an anti-tumor response." (PMID 23554566, 2013). "Here we show, using two non-immunogenic murine tumor models, that treatment with gemcitabine chemotherapy in combination with CTLA-4 blockade results in the induction of a potent anti-tumor immune response." (PMID 23626745, 2013). "Considering the association between the studied CTLA-4 polymorphisms and clinicopathological features of NSCLC, including histopathological type of cancer, tumor stage, and patients' gender, we did not observe any significant differences." (PMID 23936819, 2013). "A recent study demonstrated that antibodies against CTLA-4 (anti-CTLA-4) induce proliferation of TCR stimulated T effector cells and abrogate Treg suppressive activity by enhancing IL-2 and IFNγ release in response to polyclonal or tumor antigen stimulation." (PMID 23861693, 2013). "In particular, CTLA-4/B7 blocking in murine models results in increased IL-2 and interferon-gamma (IFN-γ) production by lymphocytes, increased expression of major histocompatibility complex (MHC) class I molecules, and markedly increased tumor killing." (PMID 23634660, 2013). "GVAX + anti-CTLA-4 mAb combination therapy did not reduce the number of tumor antigen-specific Tregs." (PMID 23557194, 2013). "For example, simultaneous blockade of CTLA-4 and PD-1 was shown to reduce the frequencies of TREG cells and to increase the numbers of effector TILs in mice bearing established B16.F10 melanoma, improving the efficacy of tumor vaccines." (PMID 23616948, 2013). "Based on these data, we evaluated the ability of a CTLA-4 blocking monoclonal antibody to augment vaccine-mediated proliferation, once again using either non-transgenic, or tumor bearing mice (ProHA × TRAMP)." (PMID 23557194, 2013). "Neutralizing the key inhibitory check point CTLA-4 permits extensive primary T cell activation, but by itself is not sufficient for driving an anti-tumor immune response, especially in the case of advanced tumors." (PMID 23450201, 2013). "As in non-transgenic mice, the lytic response in tumor-bearing mice was optimal when anti-CTLA-4 was administered after vaccination." (PMID 23557194, 2013). "Hence, we evaluated the effects of CTLA-4 blockade and GVAX combination therapy on the tumor antigen-specific Teff and Treg populations within the tumor and tumor-draining lymph nodes in our ProHA × TRAMP model." (PMID 23557194, 2013). "Blockade of CTLA4 or PD-1 in combination of TLR9 agonist CpG ODN treatment overcomes immune tolerance in tumor bearing mice with improved long-term survival, increased tumor-specific effector T-cell population and decreased Treg cell levels." (PMID 22737174, 2012). "Anti-CTLA-4 antagonist mAb (ipilimumab) does not reduce Treg cell numbers but instead preferentially exclude Tregs from the tumor lesion, so as to increase the intratumoral Teffector/Treg ratio and improve therapeutic efficacy." (PMID 22778760, 2012). "Since B7.1 has high affinity to CTLA-4, soluble B7.1-Fc may block CTLA-4 signaling instead of cross-linking CTLA-4, thereby sustaining the activation of tumor-specific T cells." (PMID 24955288, 2012). "Furthermore, the combination of CTLA-4 blockade and 4-1BB (CD137) activation enhanced tumor rejection by increasing T-cell infiltration, proliferation capacity, and cytokines production." (PMID 22548114, 2012).
tumor (continued). "CTLA-4 abrogating antibodies do not impact on vaccine-specific immune responses and even when administered with a peptide vaccine, tumor antigen-specific responses were only modestly increased." (PMID 22788688, 2012). "Ipilimumab blocks the negative cytotoxic T-lymphocyte antigen (CTLA)-4 that enhances T-cell responses to tumor cells, leading to effective immune responses." (PMID 23234250, 2012). "While in the TC-1 tumor model, anti-CTLA4 injection significantly delayed tumor growth, it had no therapeutic effect in the MMC tumor model." (PMID 21779410, 2011). "Again these studies suggest that anti-CTLA4 has no therapeutic effect in tolerized tumor models, although it appears to increase the number of intratumoral effector T-cells." (PMID 21779410, 2011). "The synergistic effect on tumor growth was mirrored with increased tumor infiltration of CD8+T cells expressing CTLA-4 and PD-1, presumably without treatment these cells would have been anergized." (PMID 24212948, 2011). "Especially nTregs constitutively express CTLA-4 and its blockade by non-depleting humanized monoclonal antibodies ipilimumab and tremelimumab has the potential to restore anti-tumor immunity." (PMID 24212779, 2011). "Repeated combination treatment upon rebound of CA-125 over seven years has helped control the tumor and demonstrates the lack of tumor resistance to CTLA-4 blockade." (PMID 21281484, 2011). "Induction of anti-CTLA4 expression in vivo was confirmed on the mRNA level by qRT-PCR and protein level by ELISA with tumor lysates (data not shown)." (PMID 21779410, 2011). "Tumor cells can escape the immune system by overexpressing molecules of the B7 family, e.g. B7-H1 (PD-L1 or CD86), which suppresses the anti-tumor T-cell responses through binding to the PD-1 receptor, and similarly for B7.1 (CD80), through binding to CTLA-4." (PMID 21884581, 2011). "To understand why anti-CTLA4 in these models did not suppress tumor growth, we performed flow cytometry and immunofluorescence analyses of immune cells in the spleen and the tumors." (PMID 21779410, 2011). "Lack of efficacy can be explained by well-defined tumor escape mechanisms, which are currently being addressed by combining DC vaccination with other approaches, such as CTLA4 or CD25 blockade." (PMID 21533099, 2011). "The central findings from our studies are i) anti-CTLA4 therapy is inefficient in the tolerized MMC model and ii) in both tumor models, anti-CTLA4 expression mediated by the HSC delivery approach not only failed to exert anti-tumor effects, but increased the rate of tumor growth." (PMID 21779410, 2011). "Ipilimumab is a humanized monoclonal antibody blocking CTLA-4, engineered to contrast the negative immune regulation, thus increasing quantity and duration of the immune effector response against tumor cells." (PMID 22235224, 2011). "It has been reported that antibodies against CTLA-4 (anti-CTLA-4) induce proliferation of TCR-stimulated T effector cells and abrogate Treg suppressive activity by enhancing IL-2 and IFNγ release in response to polyclonal or tumor antigen stimulation." (PMID 22162710, 2011). "In any case, the combined blockade of CTLA-4 and GITR with mAb was recently shown to synergistically reduce tumor formulation in two different murine tumor models, demonstrating that their respective effects on Tregs and effector T cells, in the end, work together." (PMID 24212948, 2011). "The critical questions for further clinical development of anti-CTLA-4 to be answered are: the mechanisms involved in the anti-tumor effects; how to distinguish responders from non-responders; the best combinations with conventional therapies or vaccines." (PMID 19175928, 2009). "It was shown that Teff cells are the major population accountable for the anti-tumor effects of anti-CTLA-4; CTLA-4 blockade in Tregs alone does not significantly contribute to tumor control; while blocking CTLA-4 in both populations is necessary for an optimal anti-tumor response." (PMID 19175928, 2009).
tumor (continued). "Despite a wealth of knowledge about the antitumor activity induced by CTLA4 blockade in animal models, the mechanisms that mediate tumor regression in human patients are currently not fully understood." (PMID 18452610, 2008). "Finally, we report that both tumour ablation techniques can be efficiently combined with immuno-modulatory approaches, like blockade of CTLA-4 signalling or regulatory T-cell depletion, to induce functional CD8+ T cells creating systemic anti-tumour-immunity." (PMID 16953240, 2006). "Importantly, combined CTLA-4 and PD-1 blockade reactivated anti-tumor T cell features in non-responders in vitro, highlighting CTLA-4 as a potential driver of resistance." (PMID 42291216, 2026). "Baseline tumour immune profiling revealed that protumoural activated regulatory T (Treg) cells and M2 macrophages predict durable clinical benefit, regardless of the anti-CTLA4 administration route." (PMID 42056527, 2026). "TG6050, an oncolytic vaccinia virus (OVV) encoding IL-12 and anti-CTLA-4 (@CTLA-4), allowed prolonged intra-tumoral expression of IL-12 and @CTLA-4 at effective levels without systemic toxicity and promoted tumor regression through significant immune remodeling of the TME." (PMID 40821119, 2025). "Given its ability to engage both T cell activation and potential ADCC via NK cells, combining cosibelimab with other ICIs, such as CTLA-4 inhibitors or newer agents targeting LAG-3 or TIGIT, could synergistically overcome resistance mechanisms and improve anti-tumor immune responses." (PMID 40299523, 2025). "A study demonstrated that cordycepin synergizes with CTLA-4 suppressant to alter the responsive and depletion condition of CD8T cells, thus enhancing CD8 T cell-mediated tumor microenvironment (TME) anti-tumor immunity, remodeling the tumor microenvironment, and enhancing cancer immunotherapy." (PMID 40129987, 2025). "Recently, there has been active research into vaccine combinations involving checkpoint inhibitors, such as anti-CTLA-4 or anti-PD-1/PD-L1, to enable the vaccine-induced T cells to enter the tumor and function there without being inhibited by ligands like PD-L1." (PMID 40625850, 2025). "In addition, anti-CTLA4 and anti-PD-1 ICI could counteract the immunosuppressive effects induced by RHRT, thus favoring the final effective activation of the anti-tumor immune response." (PMID 40236706, 2025). "Furthermore, the presence of CTLA4+IFN-γ+ lymphocytes, particularly in SCC, may serve as a biomarker for tumor progression and a potential target for future immunotherapy strategies aimed at modulating the immune response in NMSN." (PMID 40005446, 2025). "One notable observation was that in addition to anti-tumour activity, the application of anti-CTLA-4 antibodies established a specific protective memory response against the tumour following treatment with anti-CTLA-4 antibodies, opening the possibility of a post-tumour vaccination effect." (PMID 40265076, 2025). "Importantly, compared to using only one regimen, combination of MNX1 depletion with anti‐CTLA‐4 antibody significantly inhibited the tumor growth, indicating that targeting MNX1 may be a potential method to enhance the therapeutic efficacy of CTLA‐4 inhibitor." (PMID 39912421, 2025). "The overexpression of CTLA-4 by iTregs, which, upon interaction with CD80/CD86 on dendritic cells, could suppress T lymphocyte activation or induce anergy in effector T cells, thereby diminishing anti-tumor immunity." (PMID 41203944, 2025). "Second, the induction phase of ipilimumab plus nivolumab provides repeated CTLA‐4 blockade, in contrast to the single priming dose of tremelimumab in STRIDE, and may enhance de novo priming, expand tumor‐reactive clones, and reduce intratumoral regulatory T cells." (PMID 41446458, 2025). "Furthermore, PTGER4's negative correlation with immune checkpoints (PDCD1, CTLA4) underscores its potential to counteract immune exhaustion, a phenomenon critical for sustaining anti‐tumour immunity." (PMID 41284374, 2025).
tumor (continued). "In contrast, anti-CTLA-4 antibodies not only block ligand engagement by binding CTLA-4 with high affinity but may also deplete or functionally inhibit Tregs within the TME, thereby alleviating immunosuppression and potentiating anti-tumor immunity." (PMID 41425253, 2025). "Similarly, mRNA vaccines encoding MUC1-hemagglutinin (HA) Tag in LCP nanoparticles have demonstrated successful expression in 4T1 cells and lymph nodes, augmenting tumor-infiltrating CD8+ T-cells and reducing tumor size when combined with anti-CTLA-4 in mouse models." (PMID 40281554, 2025). "In addition, to investigate the potential of ME1 as a target for tumor immunotherapy, we analyzed the overall survival rates of patients exhibiting high versus low expression of ME1 following treatment with anti-PD1, anti-PDL1, or anti-CTLA4 therapies." (PMID 40510340, 2025). "Thus, high CTLA-4 expression in this setting presumptively reflects a tumor microenvironment with high infiltration of activated immune cells, as opposed to CTLA-4 expressing regulatory T cells and exhausted cytotoxic T cells." (PMID 39751903, 2025). "Since ICIs treatment relieves T cell tolerance mediated by PD-1/PD-L1 or CTLA-4, CD8+ T cells that originally remained unresponsive to these “self” antigens are activated, thus triggering cross-attacks on normal melanocytes expressing the same antigens (on-target, off-tumor effect)." (PMID 40861456, 2025). "Immunotherapy can accentuate the effect created by SABR alone via checkpoint inhibition (PD-1 and CTLA4) or targeting other immune pathways such as GITR (glucocorticoid-induced tumour necrosis factor-related protein acts as a co-stimulatory receptor), promoting anti-tumour responses." (PMID 41226343, 2025). "As Treg are the dominant CTLA4-expressing CD4 T cell that could productively interact with MHCII and CD80/86 expressing macrophages, it is notable that these cells have been shown to expand in proportion in the tumor at later timepoints following RT." (PMID 41417245, 2025). "However, CTLA-4 inhibitors act predominantly by enhancing the binding affinity between CD28 on T cells and B7-1/B7-2 on antigen-presenting cells (APCs), indirectly augmenting T cell anti-tumor activity." (PMID 40783512, 2025). "Treatment with anti-CTLA-4 alone did not significantly affect PD-L1 levels in tumor tissues." (PMID 39961271, 2025). "Interestingly, CXCL6 and other ARGs also showed negative correlations with checkpoints like VEGFB, KIR2DL1, LAG3, CTLA4, PDCD1, and IFNG, indicating they may promote immune surveillance and anti-tumor responses." (PMID 40943183, 2025). "Combined blocking of PD-1/PD-L1 and CTLA-4 negative co-stimulatory pathway can make tumor-specific T cells that would otherwise be inactivated continue to expand and play an effective role, thus transforming the tumor microenvironment from an inhibitory state to an immune response state." (PMID 39958358, 2025). "Given that PD-1 and CTLA-4 are predominantly expressed on activated or exhausted T cells, their bulk tumor expression largely reflects T-cell infiltration and activation rather than tumor-intrinsic checkpoint regulation." (PMID 41291343, 2025). "Furthermore, CTLA4+ T cells may produce S100A4, promoting the stemness of TNBC cells Targeting CHI3L1 to restore the tumor-killing activity of CD8+ T cells might be a viable approach for treating TNBC." (PMID 40097979, 2025). "Hence, it may be postulated that treating patients with both anti-CTLA-4 and anti-CD80 antibodies may lead to a similar response rate in human tumours to that observed in mouse tumours." (PMID 40725864, 2025). "Interestingly, while succinylation levels were elevated in tumor-proximal immune cells, overall succinylation scores in CRC showed a negative correlation with the expression of immune checkpoint molecules such as PDCD1 (PD-1), CD274 (PD-L1), and CTLA4." (PMID 40463370, 2025).